SMAD2 (SMAD family member 2)
Diseases named in the same sentence as SMAD2 in open-access papers (continued):
Sharing a sentence is not in itself a finding about the gene and the disease.
tumor (continued). "The authors clarified that, in SMAD4-positive tumor cells, the SMAD2/3/4 complex can induce the expression of EMT-associated transcription factors such as SNAIL, which contributes to EMT." (PMID 29254283, 2017). "Concomitant with this expression was a corresponding loss of phosphorylated SMAD2 within the tumor tissue in 5 out of 6 invasive SCC." (PMID 28219480, 2017). "In advanced CRC, increased TGF-β levels are associated with poor prognosis due to the induction of Smad2 accumulation in tumor stromal cells, which results in increased survival of metastatic cells and organ colonization." (PMID 25980495, 2015). "As somatic abnormalities in functions known to be regulated by the TGF-β/Smad2/3 pathway underlie tumor suppression and metastasis, this research also provides a resource for miRNAs involved in cancer." (PMID 23390484, 2013). "By immunostaining, 70% human skin SCC show Smad2 protein reduction/loss in tumor tissues, especially, the incidence of Smad2 loss is higher in poorly differentiated SCCs." (PMID 22204491, 2011). "Nearly identical to the controls, the Smad2 and inhibin alpha double knockout mice succumbed to weight loss, aggressive tumor progression, and death." (PMID 20565978, 2010). "Consequently, the TGFβ1/Smad2/3 signaling pathway drives the transdifferentiation of GC-MSCs into cancer-associated fibroblasts (CAFs)-promoting stromal remodeling and tumor aggressiveness." (PMID 42114147, 2026). "In addition, the CRC patients with both periostin-positive and Smad2/3-positive CAFs were closely associated with venous invasion, tumor relapse, and a highly advanced stage." (PMID 39941916, 2025). "The presence of TAM and CAF with evidence of activation of the TGF-β1/TAK1/NF-κB/SMAD2 pathway in NB tumours could thus be a biomarker identifying tumours at higher risk of developing drug resistance." (PMID 38806726, 2024). "Thus, loss of SMAD4 tumor suppressive activity in PDAC leads to an oncogenic gain-of-function of SMAD2/3, and to the onset of associated deleterious effects." (PMID 36207615, 2022). "In a preclinical model, a TGF-β inhibitor, SRI31277, was administered to mice with multiple osteolytic lesions and was shown to decrease the tumor burden and decrease phosphorylated SMAD2, which was associated with decrease in osteoclasts and increase in osteoblasts." (PMID 34201396, 2021). "Furthermore, loss of tumor suppressive miR-19a-3p leads to activation of SMAD2 and SMAD4, contributing to the formation of bone metastasis in a mouse model." (PMID 31842336, 2019). "SMAD2 mutations occur in approximately 3–6% of CRC tumor cases." (PMID 31827763, 2019). "In glioma, orthotopically implanted β8-high astrocytoma cells develop microscopic non-haemorrhagic tumours with uniform vessels, whereas β8-low cells cause large haemorrhagic tumours with an abundant vasculature and a lower Smad2/3 expression in endothelial cells, implying TGFβ-mediation." (PMID 31438626, 2019). "The decrease of SMAD2 under TGFβ/hypoxia in tumor-associated macrophages may add to their roles supporting angiogenesis and tumor progression." (PMID 26146544, 2015). "Notably, the loss of one Smad2 allele is sufficient to promote tumor formation and malignant progression." (PMID 25170969, 2014). "The current results revealed that aberrant TGF-β1 was associated with Smad2 and Smad7 expression in tumor tissues, and that direct coculture GC cells with PBMCs could promote the expression of Smad2 and Smad3." (PMID 23342108, 2013). "Using these models, we have shown that Smad4 functions as a potent tumor suppressor and its loss causes spontaneous SCCs development; Smad2 functions as a tumor suppressor and its loss promotes SCC formation initiated by other genetic insults but is insufficient to initiate tumor formation." (PMID 22204491, 2011).
tumor (continued). "Furthermore, survival analyses revealed that the effects of SMAD2 linker phosphorylation depend on its cellular context: A low level within immune cells drives beneficial outcome compared to increased risk of death or relapse if happening in tumour cells." (PMID 40319202, 2025). "Among the altered genes, BNC2 is a putative tumor suppressor; RASA1 gene (Ras p21 protein activator 1) is the regulator of Ras oncogene, and mutation in RASA1 may turn on oncogenic pathways; Smad2 is a tumor suppressor; and Yap1 is an oncogenic co-activator in the Hippo pathway when overexpressed." (PMID 36865791, 2023). "Finally, we investigated whether nuclear translocation of SMAD2/3 caused by PTEN had a tumor-suppressive or tumor-promoting function." (PMID 34638474, 2021). "Especially given that the system provided high probabilities of activated TGF-β signalling in some areas containing tumour cells with less p-SMAD2, our diagnostic system could identify the possibility that tumour cells in those areas have acquired malignant phenotypes induced by TGF-β." (PMID 32020064, 2020). "Hence, the mapping of the cancer related mutations onto the surface of the MH2 domain of Smad2 implies that these mutations alter the formation of homo/hetero complex formation and hence might affect the tumor suppressor roles of Smad proteins." (PMID 31323058, 2019). "CD133 expression in tumor cells might be associated with TGF-β1-p-Smad2-EMT axis in ICC." (PMID 29510695, 2018). "This drives M2-like polarization and Smad2-mediated transcription of tumor necrosis factor-α (Tnf-α), which activates Nf-κB in neighboring tumor cells, conferring chemoresistance." (PMID 41975075, 2026). "Both the periostin-positive tumor stroma group and the Smad2/3-positive cancer cells group showed significant correlations with venous invasion (p = 0.023), a high relapse rate (p = 0.014), and a high advanced stage (p = 0.035)." (PMID 39941916, 2025). "Depletion of PSMB8 or TMZ combination inhibited GBM tumor growth by reducing the downstream protein expression and SMAD2 phosphorylation of the TGF-β pathway." (PMID 40335825, 2025). "In mesenchymal CS (MSC), high levels of phosphorylated SMAD2 (p-SMAD2) have been observed in the tumor’s small cell components." (PMID 40867318, 2025). "In vivo models confirmed that the overexpression of tricellulin facilitated tumor growth and activated the TGFb1/ SMAD2/3 pathway in CRC." (PMID 40291908, 2025). "In this study, inhibition of ALK5 by the kinase inhibitor LY2157299 disrupted Smad2/3 signaling (supposedly leading to tumor suppression) but not non-Smad signaling via the toll-like receptors (TLRs, contributing to tumor progression)." (PMID 40260391, 2025). "Other factors presumably generated by the ENG‐primed TGF‐β‐Smad2/3 autocrine signaling in myCAFs would also mediate primary tumor growth promotion by these fibroblasts." (PMID 40644310, 2025). "The expressions of periostin and Smad2/3 in the tumor specimens were examined by immunohistochemistry." (PMID 39941916, 2025). "ShRNA-mediated NRP1 knockdown in KRAS wildtype cells increased cell viability and tumor growth by decreasing the SMAD2 phosphorylation, whereas a KRAS mutant reverses the increased viability and leads to tumor inhibition." (PMID 40277760, 2025). "In the tumor stroma, Smad2/3 was expressed primarily in the cytoplasm or nucleus of CAFs rather than in the ECM." (PMID 39941916, 2025). "KLF4 upregulation combined with Notch3, HER3, and p-Smad2 downregulation disintegrated the regulatory network of tumor stemness from multiple dimensions." (PMID 40438682, 2025). "This is very concerning, as it was reported that GRP78 and CRIPTO overexpression in the cancer cells activate MAPK/AKT signaling, Src/PI3K/AKT, and Smad2/3 pathways leading to tumor proliferation, plasticity, and resistance to apoptosis." (PMID 40360533, 2025).
tumor (continued). "RUNX3 plays a crucial role in TGF-β signaling via binding with Smad family including Smad2, Smad3 and Smad4 and tumor suppression pathways." (PMID 40354349, 2025). "We show miR-590-3p functions as a tumor suppressor that promiscuously blocks multiple SMAD2/3 targets downstream of TGFBR2 in GBM neurospheres." (PMID 40301302, 2025). "Periostin, a matricellular protein, was reported to be expressed on both cancer cells and surrounding tumor stromal cells, such as CAFs, and is regulated by Smad2/3 signaling." (PMID 39941916, 2025). "In this context, miRNAs inhibiting expression of PTEN (miR-425 and miR-148a) should be considered as oncomirs, and those inhibiting KRAS, EGFR, PIK3CA, TGFBR1, and SMAD2 (let-7g, miR-150, miR-128, miR-139, miR-148a, miR-148b) as tumor suppressors." (PMID 40868120, 2025). "TGF‐β1 was identified as a key mediator, with its upregulation in tumor cells activating the TGF‐β‐SMAD2/3 pathway in fibroblasts." (PMID 39739618, 2025). "We first assessed the abundance of Smad2/3 signaling in tumor MDSC derived from CT26 tumor-bearing mice." (PMID 41360769, 2025). "TGF-β signaling pathway associated with angiogenesis in various phases of carcinoma, such as carcinogenesis, tumor growth, and distant metastasis via nuclear translocation of Smad2." (PMID 39941916, 2025). "On the other hand, we observed that SMAD2/3 phosphorylation was increased in 4T1 tumor cells 48 hours after treatment with CDDP or CDDP-Eri." (PMID 40590231, 2025). "Inhibiting ENG on myCAFs suppressed the TGF‐β‐Smad2/3 pathway, reducing primary tumor growth and metastasis." (PMID 40644310, 2025). "HRAS and SMAD2 were reported to promote EMT in tumor cells, but the mechanism of the interaction between these 2 proteins is not clear." (PMID 39913299, 2025). "High levels of KRT7 are associated with higher tumor grades, advanced stages, and poor prognoses, likely due to its role in promoting proliferation and EMT via the TGF-beta/SMAD2/3 signaling pathway." (PMID 41465326, 2025). "SNHG1 has been reported to promote CRC cell proliferation and invasion by sponging tumor-suppressive miRNAs, epigenetic regulation and modulating SMAD2 signaling." (PMID 41357316, 2025). "In contrast, tumor-suppressive miRNAs, such as miR-132 and miR-422a, inhibit TGF-β-induced EMT by targeting pathway components, including TGF-β1, SMAD2, and associated EMT markers." (PMID 40806457, 2025). "Here, we show that TGF-β signalling is highly active in iCCA and exerts a prominent suppressor effect on tumour cell lines and organoids established from iCCA metastases biopsies, that relies on a functional canonical SMAD2/3/4 signalling." (PMID 40820091, 2025). "This complex activates MAPK/AKT signaling, Src/PI3K/AKT, and Smad2/3 pathways which is a reason for tumor proliferation." (PMID 40360533, 2025). "ALK7 has multiple physiological functions, including metabolic regulation, macrophage activation and tumor suppression, primarily through the Smad2/3 signaling pathway." (PMID 39948368, 2025). "In most analyzed populations—both within the liver and tumor microenvironments—SMAD2–3 and TAK1 activation appears to be mutually exclusive." (PMID 41268557, 2025). "Immunohistochemistry results showed that TGFβ1 and SMAD family member 2 (Smad2) were expressed both in cancer cells and stromal cells, including lymphocytes, plasma cells, macrophages, and fibroblasts, in the tumor microenvironment." (PMID 40899568, 2025). "As uncovered by our results, the maintenance of p27 expression in hPSCs via SMAD2/3-NANOG-OCT4 is particularly interesting considering the dual role of p27 as a tumor suppressor as well as an oncogene." (PMID 38758030, 2025). "H. pylori infection can activate the epithelial-mesenchymal transition (EMT) pathway, promoting tumor invasiveness through the TGF-β1/Smad2 signaling cascade and remodeling the tumor microenvironment to enhance immune evasion." (PMID 41338460, 2025).
tumor (continued). "The immunostaining demonstrated that exposure to tumor cell-derived CM significantly increased SMAD2 phosphorylation in OCs (4T1 CM: 4.3-fold increase; MDA CM: 3.7-fold increase)." (PMID 41249489, 2025). "Our results from NSCLC patient tissues indicate that SMAD2 linker phosphorylation is increased within panCK+ tumour cells compared to panCK+ cells within tumour-free lungs." (PMID 40319202, 2025). "The delivery of miR-142 downregulated PD-L1, promoted M1-like macrophage polarization, suppressed EMT by reducing Smad2/3 and Snail expression, and restored E-cadherin, limiting tumor migration." (PMID 41304839, 2025). "Consistent with the in vitro data, anti-Mstn treatment effectively reduced tumor cell-induced SMAD2 phosphorylation in bone tissue." (PMID 41249489, 2025). "In the TGF-Beta pathway, SMAD2 mutations were more frequent in H/L patients, while SMAD4 mutations were more common in NHW patients, indicating potential differences in tumor suppressor pathway disruption." (PMID 40869017, 2025). "Platelet-derived TGF-β1 also induces epithelial–mesenchymal transition (EMT) through the Smad2/3 pathway, enhancing tumor cell migration and invasion." (PMID 41458591, 2025). "Another study showed that decreased expression of TP73-AS1 reduced tumor size and downregulated SMAD2 gene expression, suggesting that it regulates SMAD2 gene expression by targeting miR-329-3p to promote CC cell proliferation." (PMID 40332793, 2025). "The SMAD2/3/4 complex, which is located in the nucleus, induces tumor‐promoting actions via stimulating cell proliferation." (PMID 40584407, 2025). "In cancer, SMAD2 exhibits dual roles: it can function as a tumor suppressor by inhibiting cell proliferation, and conversely, it can promote metastasis by facilitating epithelial-to-mesenchymal transition (EMT)." (PMID 39842382, 2025). "Overall, SMAD2 linker phosphorylation was more common in NSCLC (stroma = 91.81% & tumour = 95.75%) than in tumour-free lung tissues (6.25%)." (PMID 40319202, 2025). "Previously, we described CAFs as progressively increasing TGF‐β‐Smad2/3 signaling in an autocrine fashion during tumor progression, resulting in the acquisition of myofibroblastic abilities." (PMID 40644310, 2025). "Mechanistically, TGF-β signaling via Smad2/3 phosphorylation suppresses pro-inflammatory pathways while upregulating arginase-1 and MMPs, facilitating tumor angiogenesis and extracellular matrix degradation, thereby promoting metastasis." (PMID 40387965, 2025). "To find the cause of the low expression of TAT in HCC, we focused on the TGF-β/Smad2/3/4 signaling pathway, which also acted as a tumor suppressor in cancer." (PMID 38769521, 2024). "In the TGFβ pathway, co-occurring mutations were found in SMAD2 and SMAD3 (FDR-adjusted P = 1.03 × 10−10) in nHM tumours, whereas TGIF1 co-occurred with PIK3CA (FDR-adjusted P = 0.09) in the HM cases." (PMID 39112715, 2024). "We had previously observed an increased expression of p-SMAD2 in tumours generated in NSG mice by the co-injections of human NB cells and human MN and MSC." (PMID 38806726, 2024). "The results demonstrated that SKP1 was highly expressed in tumour tissues, whereas Smad2 and BMPR2 were inhibited, which was consistent with the findings of scRNA‐seq data." (PMID 39548559, 2024). "In particular, Smad2, 3 and 4 play a central role in mediating the TGFβ tumor-suppressive activities in multiple types of cancer." (PMID 38201651, 2024). "The tumor-suppressive role of TGF-β signaling via the canonical pathway is mediated by Smad2 and Smad3." (PMID 38256080, 2024). "The correlation between NF-κB p65 activation and αSMA+ cells and p-SMAD2 in primary NB tumours and the more abundant presence of p-NF-κB in TME-rich tumours provides support to our in vitro data." (PMID 38806726, 2024).
tumor (continued). "Recapitulating, nonencapsulating metastases present greater stromal immunosuppressive activity based on the greater presence of myeloid cells and greater phosphorylation of SMAD2 in both the stroma and the tumor." (PMID 39563958, 2024). "This combination therapy improves prognosis by inhibiting Treg cells in tumor-draining lymph nodes and spleen and through the inactivation of p-SMAD2 and Neuropilin-1." (PMID 39534084, 2024). "To examine the impact of BA treatments on TGF-β signalling in this HGSC tumour model, we performed immunoblotting with phosphorylation-specific Smad2/3 (pSmad2/3) or pan-Smad2/3 antibodies on lysates from ascites cells (α-Actinin served as a loading control)." (PMID 38622286, 2024). "Coculturing with neurons not only enhanced the proliferation, migration, and invasion but also upregulated TGFβ-SMAD2 signaling and PD-L1 expression of tumor cells." (PMID 38324026, 2024). "In nude mice tumor formation model, the tumor grew faster when breaking the Smad2/3/4 complex formation." (PMID 38769521, 2024). "In this review, we focus on Smad2 function and its modulation by Smad3, which is often antagonistic to Smad2 in the context of tumor progression." (PMID 38569937, 2024). "TGF-β-induced Smad2 phosphorylation levels are high in the vascular compartment of tumor tissue and its expression is correlated with increased tumor volume and reduced survival in mice." (PMID 38892305, 2024). "Overall, however, the evidence supports that Smad2 suppresses, whereas Smad3 promotes tumor development, malignant progression, and metastasis in several types of cancer, although the underlying mechanisms are divergent." (PMID 38569937, 2024). "Because Smad2 global knockout mice are embryonic lethal, Smad2 heterozygous mice were analyzed for tumor formation." (PMID 38569937, 2024). "The result of the MOC1 cell line was also consistent with that in the SCC-15 cell line and showed that both galunisertib inhibited migration/invasion activities induced by neural coculture and downregulated TGFβ-SMAD2-PD-L1 pathway in tumor cells." (PMID 38324026, 2024). "To verify the biological function of the TGFβ-SMAD2 axis in the neuron-tumor coculture system, we took the advantage of a small-molecule inhibitor of TGFβ receptor type I (TGFβRI) kinase galunisertib to inhibit the TGFβ signaling in tumor cells." (PMID 38324026, 2024). "We utilised adenoviruses to efficiently transduce tumour cells with the specific Smad1/5 inhibitor Smad6 (Ad-Smad6-M2 adenovirus) or the Smad1/5 and Smad2/3 inhibitor Smad7 (Ad-Smad7-M2 adenovirus)." (PMID 39724753, 2024). "We also detected the enrichment of proteins interacting with the ubiquitination pathway (e.g. tumour suppressors SMAD2, APC, and AXIN1)." (PMID 39660592, 2024). "Because Smad2 mutations are found in various cancers although at a low frequency, Smad2 is thought to have tumor-suppressive functions." (PMID 38569937, 2024). "We found that only Smad2flox/flox;Smad3flox/flox mice with intrauterine Ad-cre injection and E2-pellets developed tumors, confirming that E2 is necessary for tumor development in Smad2/3 cKO mice." (PMID 36906706, 2023). "The results of this study are consistent with those of other studies, suggesting that low expression of SMAD2 is correlated with clinical malignancy and affects tumor immune microenvironment." (PMID 36969909, 2023). "Because Ltf-cre activity is E2-dependent, we also tested the effect of E2 on tumor development independently of Ltf-cre by using adenoviral-mediated deletion of SMAD2/3." (PMID 36906706, 2023). "The activated TβRI can specifically recognize downstream Smad2 and Smad3, bind to and activate them, and the activated Smad2 and Smad3 dissociate from TβRI and then form heterologous complex with tumour suppressor gene Smad4." (PMID 37431884, 2023).